RHOA (ras homolog family member A)
Diseases named in the same sentence as RHOA in open-access papers (continued):
Sharing a sentence is not in itself a finding about the gene and the disease.
glomerular disease (5 papers, 2018 to 2023). "RhoA and Rac1 play key roles in regulating cytoskeletal dynamics in podocytes, and dysregulating the activity of these small GTPases in glomerular disease processes causes proteinuria." (PMID 35991898, 2022). "Indeed, RhoA and Rac1 play key roles in regulating cytoskeletal dynamics in podocytes, and dysregulated activity of these small GTPases in glomerular disease processes causes proteinuria." (PMID 31877991, 2019). "Reorganization of the actin cytoskeleton and of cell-matrix adhesions towards a contractile and mechanically enforced RhoA-dependent actomyosin cytoskeleton is a common pattern in podocytopathy and considered a driving factor of glomerular disease." (PMID 37443829, 2023). "Rho GTPase family members such as RhoA, Rac1, and Cdc42 play key roles in glomerular disease processes." (PMID 31877991, 2019). "In addition, several cytoskeletal proteins of RhoA upstream modulators are found to be involved in hereditary glomerular diseases, suggesting that inappropriate activation of RhoA is significant both physiologically and pathologically." (PMID 36096674, 2022). "Detection of increased levels of ARHGAP29 in early disease stages of human glomerular disease implies a novel negative feedback loop for mechanotransductive RhoA—YAP/TAZ signaling in podocyte physiology and disease." (PMID 37443829, 2023).
HIV-1 infection (5 papers, 2014 to 2023). The type species of lentivirus and the etiologic agent of acquired immunodeficiency syndrome (AIDS). "Collectively, this study has reinforced the importance of the cytoskeleton in optimal HIV-1 infection of host cells and implicated RhoA, Cdc42, and ROCK as host dependency factors for viral replication." (PMID 28114951, 2017). "Differentiated MDM were infected for 4 h and treated 1 h prior to or 4 h after HIV-1 infection with CT04 (1 μg/ml) and NSC (75 μM), RhoA or Rac1 GTPase inhibitors, respectively." (PMID 26379653, 2015). "Inhibition of both RhoA and Rac1 GTPases resulted in 48 ± 2% decrease in HIV-1 RT activity, when inhibitors were applied prior to HIV-1 infection of MDM, whereas post-infection treatment with Rho GTPase inhibitors led to 85 ± 3% diminution in HIV-1 RT." (PMID 26379653, 2015).
hyperlipidemia (5 papers, 2013 to 2022). "In summary, the present study demonstrated that GLXB is able to relieve I/R-induced myocardial injury for the hyperlipidemia subject with an efficiency similar to simvastatin, a potential that is likely related with regulating energy metabolism involving RhoA/ROCK signaling pathway." (PMID 29674972, 2018). "The hyperlipidemia compensatory effect of statin therapy could be observed for few proteins, three of them being involved in both actin cytoskeleton and focal adhesion regulation pathways: alpha-actinin-1, transforming protein RhoA and integrin alpha-1 besides the ras-related protein Rap-1A." (PMID 26628893, 2015).
injury (5 papers, 2017 to 2025). Damage inflicted on the body as the direct or indirect result of an external force, with or without disruption of structural continuity. "In summary, the activation of the LPAR1/RhoA/ROCK pathway drives demyelination in the DRG, thereby playing a significant role in the development of allodynia and hyperalgesia following nerve injury." (PMID 40249935, 2025). "This study further established that LPAR1/RhoA/ROCK signaling mediates NMDA receptor activation by modulating ephrinB1, thereby initiating behaviors indicative of neuropathic pain following nerve injury." (PMID 40249935, 2025). "Molecular pathways such as cAMP, MAPK, JAK/STAT, ATF3/CREB, BMP/SMAD, AKT/mTORC1/p70S6K, PI3K/AKT, GSK-3β/CLASP, BDNF/Trk, Ras/ERK, integrin/FAK, RhoA/ROCK/LIMK, and POSTN/integrin are activated after nerve injury and are considered significant players in axonal regeneration." (PMID 36551942, 2022).
Macrothrombocytopenia (5 papers, 2013 to 2026). "Crucially, it is now established that both gain‐of‐function mutations and non‐activating mutations induce macrothrombocytopenia through suppression of the αIIbβ3/RhoA/cytoskeletal signalling axis." (PMID 41503871, 2026). "Although the central role of the RhoA/cytoskeletal axis in αIIbβ3 mutation‐induced macrothrombocytopenia has been initially established, future studies still require deeper exploration." (PMID 41503871, 2026). "Inherited mutations in the MYH9 gene, which encodes nonmuscle myosin heavy chain IIa (NMMHC-IIa), give rise to the “MYH9-related disorders,” all of which exhibit macrothrombocytopenia, and have been linked to the RHOA/ROCK pathway." (PMID 28134622, 2017). "We confirmed the macrothrombocytopenia and examined the effect of this RhoA deficiency on megakaryopoiesis." (PMID 23935982, 2013). "Moreover, we have previously shown that mice with MK/platelet-specific RhoA-deficiency (RhoAfl/fl Pf4-cre, further referred to as RhoA−/−) exhibit pronounced macrothrombocytopenia." (PMID 28643773, 2017). "However, recent studies using knock‐in mice demonstrate that non‐activating αIIbβ3 mutations can also cause macrothrombocytopenia by disrupting the RhoA/cytoskeletal axis, providing the first evidence that constitutive αIIbβ3 activation is not an essential prerequisite for this disorder." (PMID 41503871, 2026). "Although the two types of αIIbβ3 mutations downregulate RhoA through different molecular mechanisms, targeted modulation of the RhoA/ROCK pathway may represent a therapeutic strategy for ITGA2B/ITGB3‐related macrothrombocytopenia." (PMID 41503871, 2026). "While the involvement of the αIIbβ3/RhoA/cytoskeletal signalling axis in proplatelet formation by megakaryocytes had been established previously, this study challenged the conventional view that spontaneous integrin activation was a prerequisite for macrothrombocytopenia." (PMID 41503871, 2026). "Macrothrombocytopenia, increased megakaryocyte ploidy, and a decreased number of megakaryocytes in the bone marrow of RhoAfl/fl PF4CRE+ mice all point to a significant role for RhoA in megakaryocyte development." (PMID 23935982, 2013). "Interestingly, these mice lacking RhoA in their megakaryocytes and platelets also developed macrothrombocytopenia." (PMID 23935982, 2013).
metabolic syndrome (5 papers, 2013 to 2025). A cluster of metabolic risk factors for CARDIOVASCULAR DISEASES and TYPE 2 DIABETES MELLITUS. "Rho-kinase, an effector protein of the small GTP-binding protein RhoA, is an important cardiovascular therapeutic target and its activity is increased in patients with metabolic syndrome." (PMID 25365359, 2014). "Patients with metabolic syndrome show higher RhoA/ROCK activity, which again might be a consequence of increased PAI-1." (PMID 39531449, 2024). "•Chronic pBOO are increased risk of infection through complex pathophysiological pathway involving nitric oxide guanosine monophosphate and RhoA/Rho-kinase, metabolic syndrome, autonomic hyperactivity, pelvic ischemia, psychological factors, imbalance of sex hormones, and inflammatory pathways." (PMID 35386771, 2022).
neuropathy (5 papers, 2016 to 2025). A disorder affecting the nervous system that manifests with pain, tingling, numbness, and/or muscle weakness. "We then analyze its interaction with RhoA to elucidate the mechanism of TRPV4 inhibition by RhoA, as well as the impact of human neuropathy mutations on TRPV4 gating." (PMID 37353484, 2023). "Strikingly, most residues mutated in TRPV4-mediated neuropathy (R237, R269, R315, and R316) are clustered at the interface with RhoA." (PMID 37353484, 2023). "Remarkably, all tested neuropathy mutations resulted in nearly complete disruption of TRPV4–RhoA interaction, whereas the skeletal dysplasia mutations displayed variably preserved interaction with RhoA." (PMID 33664271, 2021). "Given that neuropathy mutations within the convex face of the N-terminal ARD of TRPV4 disrupt RhoA interaction, we examined the interaction of RhoA with the TRPV4 N terminus." (PMID 33664271, 2021). "Finally, the inhibitory effect of RhoA on WT TRPV4 ion channel activity is abolished by TRPV4 neuropathy-causing mutations." (PMID 33664271, 2021). "We previously showed that neuropathy-causing mutations (R232C, R237L, R269C, R315W) in TRPV4 disrupt the interaction with RhoA, consistent with our structures." (PMID 37353484, 2023). "Underscoring the pathological importance of increased RhoA activity, we find that TRPV4 neuropathy mutant-induced axonal and dendritic degeneration can be rescued in vivo by genetic inhibition of the Drosophila RhoA ortholog Rho1." (PMID 33664271, 2021). "Neuropathy-causing mutations of TRPV4 disrupt this complex, leading to RhoA activation and impairment of neurite extension in cultured cells and flies." (PMID 33664271, 2021). "We also utilized the T-Rex-TRPV4 cells to demonstrate that the neuropathy mutant R269C disrupts interaction with endogenous RhoA." (PMID 33664271, 2021). "Together, these results suggest that neuropathy mutant TRPV4 can cause cytoskeletal disruption in vivo through excessive activation of RhoA, and these defects can be rescued by RhoA inhibition." (PMID 33664271, 2021). "In cases involving neuropathy-causing TRPV4 mutants, the potential reduction in interaction between RhoA and TRPV4 could potentially influence RhoA involved migration process." (PMID 39333347, 2025). "We previously showed that the cytoskeleton remodeling small GTPase RhoA interacts with TRPV435, but this interaction appears to be perturbed by neuropathy mutations resulting in increased TRPV4 channel activity, cytoskeletal remodeling, and cell process retraction." (PMID 37353484, 2023). "Together, our results uncover a complex interplay between TRPV4 and RhoA in regulating cell morphology and suggest that increased RhoA activation may be an important pathologic consequence of TRPV4 neuropathy mutations." (PMID 33664271, 2021). "Based on these collective results, we hypothesized that over-activation of RhoA might contribute to the pathogenesis of TRPV4 neuropathy, and that inhibition of RhoA could potentially rescue mutant TRPV4-mediated neuronal degeneration." (PMID 33664271, 2021). "Strikingly, we found that genetic inhibition of the activity of the Drosophila RhoA ortholog Rho1 by expression of dominant negative Rho1[T19N] rescued both dendritic and axonal degeneration with expression of neuropathy mutant TRPV4." (PMID 33664271, 2021). "Importantly, we also show that co-expression of neuropathy mutant TRPV4 with WT TRPV4 has an inhibitory effect on the interaction of WT TRPV4 with RhoA." (PMID 33664271, 2021). "We next addressed whether RhoA could suppress calcium influx via neuropathy mutant TRPV4." (PMID 33664271, 2021). "With expression of TRPV4 mutants that fail to interact with RhoA (TRPV4 E183A/C/K or D263A/L/K/N), we found increased basal and hypotonic saline-induced calcium influxes, similar to the neuropathy mutant R269C35." (PMID 37353484, 2023).
neuropathy (continued). "Given the abnormalities of MN-1 neurite outgrowth with expression of neuropathy mutant TRPV4, we were particularly interested in examining the impact of RhoA on sensory neuron morphology and degeneration in the fly model." (PMID 33664271, 2021). "We also generated recombinant TRPV4 ARD WT (hV4-ARD-WT), TRPV4 ARD R269C neuropathy mutant (hV4-ARD-R269C), and full-length RhoA." (PMID 33664271, 2021). "We next performed co-immunoprecipitation with over-expressed RhoA and FLAG-tagged WT TRPV4 alone or in combination with GFP-tagged WT or neuropathy mutant TRPV4." (PMID 33664271, 2021). "Furthermore, inhibition of RhoA restores neurite length in vitro and in a fly model of TRPV4 neuropathy, as demonstrated in a fly model of TRPV4 R269C mutant, which mimics TRPV4 neuropathy." (PMID 39333347, 2025). "However, inhibition of RhoA restores neurite length in vitro and in a fly model of TRPV4 neuropathy." (PMID 33664271, 2021). "However, RhoA FRET was significantly greater with agonist stimulation of neuropathy mutant TRPV4, with more rapid onset, longer duration, and higher peak RhoA activation." (PMID 33664271, 2021). "In contrast, neuropathy mutant TRPV4 did not inhibit basal RhoA activation (compare lanes 1 and 2 of T-Rex-TRPV4R269C blot), consistent with a requirement for binding of TRPV4 and RhoA for inhibition of RhoA activation." (PMID 33664271, 2021). "We demonstrate direct interaction of the TRPV4 ARD with inactive, GDP-bound RhoA, and further show how mutual TRPV4–RhoA inhibition and TRPV4 calcium-dependent activation of RhoA play important roles in modulating cellular outgrowth, both in cultured cells and in a fly model of TRPV4 neuropathy." (PMID 33664271, 2021). "Expression of WT TRPV4 attenuated colchicine-induced RhoA activation, whereas neuropathy mutant TRPV4 failed to exert an effect on RhoA activation in response to colchicine." (PMID 33664271, 2021). "Given our finding that WT but not neuropathy mutant TRPV4 interacts with RhoA, we next sought to determine the functional consequences of this interaction for RhoA function." (PMID 33664271, 2021).
peripheral T-cell lymphoma (5 papers, 2015 to 2021). "Some studies found that the mutation of RHOA was a genetic hallmark in AITL and peripheral T-cell lymphomas (PTCL), while the specific role of RHOA remained unknown." (PMID 31403034, 2019). "While we could find no literature regarding germline RHOA mutations, a somatic mutation, RHOA-G17V, has been reported to positively associate with peripheral T-cell lymphoma chemoresponse." (PMID 31156701, 2019).
pulmonary edema (5 papers, 2014 to 2017). Accumulation of fluid in the lung tissues causing disturbance of the gas exchange that may lead to respiratory failure. "In ECs, the conditional knockout of FAK or the RhoA inhibitor RhoGDI is sufficient to increase EC permeability and cause pulmonary edema in mice." (PMID 27795403, 2016). "We also have confirmed that treatment with calcitriol ameliorates seawater aspiration-induced inflammation and pulmonary edema via the inhibition of NF-κB and RhoA/Rho kinase pathway activation." (PMID 28161733, 2017). "Previous study in our lab also demonstrated that calcitriol ameliorated seawater aspiration-induced inflammation and pulmonary edema and these effects worked through inhibition of NF-κB and RhoA/ROCK pathways activation." (PMID 28161733, 2017). "This study demonstrated that attenuated high tidal volume induced-pulmonary edema was associated with reduced lung GEF-H1, active RhoA, Rho-kinase activation (p-ERM/total ERM), and p-MLC expression in lung endothelial cells." (PMID 25019086, 2014). "Thus CYP2J2-EETs is crucial for RhoA-dependent regulation of cytoskeletal architecture leading to reversible changes in vascular permeability, which may contribute to the development of new therapeutic approaches for pulmonary edema and other diseases caused by abnormal vascular permeability." (PMID 28881620, 2017). "In ANDV-infected MECs, inhibition of β3 and Rac1 and activation of RhoA may increase the duration of pore opening and thereby diapedesis alone may trigger pulmonary edema in HPS patients." (PMID 27795403, 2016).
rheumatoid arthritis (5 papers, 2016 to 2025). A chronic, systemic autoimmune disorder characterized by inflammation in the synovial membranes and articular surfaces. "We, therefore, assume that the FAK/RhoA regulatory network may be important in other SMG-induced physiological alterations, such as SMG-induced bone loss, often seen in rheumatoid arthritis." (PMID 29986550, 2018). "Ras homolog gene family member A (RhoA) plays a major role in the Wnt/planar cell polarity (PCP) pathway, which is significantly activated in patients with rheumatoid arthritis (RA)." (PMID 38022686, 2023).
type 1 diabetes (5 papers, 2012 to 2025). "Of importance, inhibition of the small GTPase RhoA, by fasudil or statins, reduces renal Nox4 protein expression in streptozotocin-induced type 1 diabetes as well as in db/db mice." (PMID 27649495, 2016). "Notable genes included RHOA that is involved in cytoskeletal dynamics, cell cycle, and cell migration, and the multifunctional proinflammatory cytokine TNF, which is also a type 1 diabetes susceptibility gene." (PMID 40113970, 2025). "Small-molecule inhibitors of RhoB have not been described, although molecules that target RhoA, Rac and Cdc42 have been, including Rac inhibitors studied in models of type 1 diabetes and collagen-induced arthritis." (PMID 28882929, 2017).
acute myeloid leukemia (4 papers, 2016 to 2022). Acute myeloid leukemia (AML) is a group of neoplasms arising from precursor cells committed to the myeloid cell-line differentiation. "It has been reported that ARHGEF3, a Rho-guanine nucleotide exchange factor (GEF) upregulated in acute myeloid leukemia (AML), modulates AML differentiation through activation of RhoA and pathways directly controlled by small GTPase family proteins." (PMID 27028992, 2016).
allergic asthma (4 papers, 2005 to 2021). A asthma with a basis in a pathological type I hypersensitivity reaction. "In the present study, a participation of RhoA-mediated Ca2+ sensitization in the augmented bronchial smooth muscle (BSM) contraction in a murine model of allergic asthma was examined." (PMID 15638941, 2005). "On the other hand, our recent study also demonstrated that a small GTPase RhoA, a Ca2+-sensitizing protein that contributes to the augmented BSM contraction in allergic asthma, is one of the targets of miR-140-3p." (PMID 33121100, 2020). "Together, this study suggests that the activation of SHP2 and RhoA/ROCK may play a significant role in regulating eosinophil recruitment in allergic asthma, and blockage of the SHP2‐RhoA signalling pathway represents a promising approach for the treatment of allergic asthma." (PMID 32355562, 2020).
anemia (4 papers, 2012 to 2023). A reduction in the number of red blood cells, the amount of hemoglobin, and/or the volume of packed red blood cells. "Noting that Mx-Cre; RhoAflox/flox mice die within eight days after polyI:C injection, likely due to severe anemia, we analyzed bone marrow B cell differentiation at day six and found that RhoA deficiency blocked CLP differentiation to proB/preB and subsequent immature B cells." (PMID 22438996, 2012). "Erythroid-specific deletion of RhoA in mice was embryonic lethal because of severe anemia, and the primitive red blood cells were macrocytic, poikilocytes and frequently multinucleated." (PMID 37179546, 2023). "The major difference was that the failure of definitive erythropoiesis in RhoA deficiency caused profound reduction in maturing erythroblasts and fetal death, whereas TSPO2 deficiency caused modest and compensated anemia." (PMID 32358067, 2020). "Finally, RhoA activity has been linked to erythroid differentiation since an overexpression of a dominant-negative form of RhoA led to anemia." (PMID 33302361, 2020).
Arthritis (4 papers, 2021 to 2024). Inflammation of a joint. "The arthritis scores in the Sh-RhoA group were significantly ameliorated after the third intra-articular injection (day 47, p=0.004) compared with those in the Sh-Ctr group." (PMID 38022686, 2023). "Of these RHO GTPases, RHOA and RAC1 regulate synovial fibroblast behavior and arthritis severity and joint damage in autoimmune arthritis." (PMID 39683640, 2024). "However, only heterozygous deletion of gene Rac1, but not Cdc42 and RhoA, could reverse inflammation in mouse models for arthritis, indicating the special role of Rac1 in chronic inflammation diseases." (PMID 34805177, 2021).